LINC00917 (long independently transcribed non-coding RNA 917)
Gene: Long non-coding RNA gene on chromosome 16 (86,331,632 to 86,349,688, reverse strand). Ensembl gene ENSG00000168367.
Diseases named in the same sentence as LINC00917 in open-access papers:
LINC00917 is named in the same sentence as 8 diseases in open-access papers, as found by Europe PMC text mining. Sharing a sentence is not in itself a finding about the gene and the disease. The quoted sentences say what the papers report.
colorectal cancer (2 papers, 2021 to 2025). A primary or metastatic malignant neoplasm that affects the colon or rectum. "LINC00917 has been linked to other diseases, including colorectal cancer (CRC), facilitating CRC proliferation, metastasis, and aerobic glycolysis through c-Myc, suggesting its potential as a therapeutic target for CRC treatment." (PMID 40565205, 2025). "The upregulation pattern of LINC00917 was in line with the discovery in human colorectal cancer." (PMID 35003204, 2021).
colorectal tumors (1 paper, 2021). "Just recently, Fattahi and colleagues identified that LINC00917 was among the genetic cluster which was aberrantly upregulated in human colorectal tumors." (PMID 35003204, 2021). "Recently, LINC00917 was found to be aberrantly expressed in human colorectal tumors." (PMID 35003204, 2021).
gestational diabetes (1 paper, 2025). Carbohydrate intolerance first diagnosed during pregnancy. "Additionally, LINC00917 has been associated with CpG sites and is suggested to be a potential biomarker for detecting gestational diabetes (GDM) in women." (PMID 40565205, 2025).
glucose metabolism disorders (1 paper, 2024). "In GDM patients, LINC00917 and TRAPPC9 methylation levels were found to be useful indicators for identifying early glucose metabolism disorders four years after delivery." (PMID 39273309, 2024).
lung carcinoma (1 paper, 2025). "Additionally, another study revealed that serum exosome LINC00917 was expressed at higher levels in lung cancer patients compared to healthy controls, demonstrating significant diagnostic value for both early-stage and advanced lung cancer." (PMID 40575159, 2025).
schizophrenia (1 paper, 2024). A major psychotic disorder characterized by abnormalities in the perception or expression of reality. "The potential involvement of nearby regulatory elements or non-coding RNAs, such as LINC00917, in brain development and mental health disorders has not been definitively confirmed, leaving the possible mechanisms linking D16S539 to schizophrenia still unclear and requiring further investigation." (PMID 39766792, 2024).
cancer (1 paper, 2021). A tumor composed of atypical neoplastic, often pleomorphic cells that invade other tissues. "Upregulated exosomal LINC00917 expression was closely associated with cancer patients’ advanced stages and shorter OSs." (PMID 35003204, 2021). "However, the expression of LINC00917 and its potential clinical implications in other human cancers are poorly explored." (PMID 35003204, 2021).
tumor (1 paper, 2021). "Furthermore, genetic and biochemical approaches are necessary to reveal the possible functional roles of LINC00917 in regulating NSCLC tumor carcinogenesis and development." (PMID 35003204, 2021). "It would be interestingly to see whether LINC00917 is also upregulated in NSCLC patients’ in situ tumor, which would provide further evidence to identify the origin of LINC00917 upregulation among NSCLC patients." (PMID 35003204, 2021). "Furthermore, multivariate analysis confirmed that tumor lymph-node metastasis [p = 0.0025, HR = 2.547, 95% CI (1.3891–4.669)] and exosomal LINC00917 expression level [p = 0.0038, HR = 2.115, 95% CI (1.2732–3.514)] may act as independent factors to predict NSCLC patients’ OS." (PMID 35003204, 2021).